CXCR6 (C-X-C motif chemokine receptor 6)
Diseases named in the same sentence as CXCR6 in open-access papers (continued):
Sharing a sentence is not in itself a finding about the gene and the disease.
melanoma (continued). "In fact, we find that a large percentage of ABCG2-positive melanoma cells with known CSC properties, also express CXCR6." (PMID 21203549, 2010). "In this report, we investigated a new candidate for a melanoma cancer stem cell (MCSC) marker, the cytokine co-receptor CXCR6, with respect to the properties of ABCG2-expressing MCSCs." (PMID 21203549, 2010). "In mouse and human melanoma, a triple-positive (CXCR3+CCR5+CXCR6+) T-cell subset is essential for tumor control, and its genetic signature correlates with positive clinical response, while a distinct CCR5+CXCR6+ subset drives liver immune-related adverse events (IRAEs)." (PMID 41415437, 2025). "In different preclinical models of melanoma, the absence of CXCR6 led to an acceleration of tumor growth." (PMID 36311728, 2022). "Expression of CXCR6 and CXCL16, comprising another significant chemokine axis, is evaluated in several cancers, such as renal, rectal, pancreatic ductal adenocarcinoma, nasopharyngeal carcinoma, and melanoma." (PMID 34298782, 2021). "In this study, we describe perifollicular and interfollicular clustering of mouse and human skin CD8 TRM cells in response to melanoma, respectively, and show that persistent clustering with DCs is required for skin TRM cell maintenance and dependent on the interaction between CXCR6 and CXCL16." (PMID 34362825, 2021). "We sort human melanoma cells using three distinct cancer stem cell (CSC) markers — CXCR6, CD271 and ABCG2 — and observe that the fraction of non-CSC-marked cells first overshoots to a higher level and then returns to the level of unsorted cells." (PMID 26494317, 2015). "IgR39 melanoma cells that are negative for CXCR6, ABCG2 or CD271 markers are sorted by flow cytometry, and then plated and grown under standard conditions." (PMID 26494317, 2015). "Therefore, herein, we have addressed the following question: Can TAAs, currently utilized as targets in melanoma immunotherapeutic protocols, be used to target ABCG2-positive or CXCR6-positive cells?" (PMID 21203549, 2010). "Thus, the relationship between melanoma formation and ABCG2 and CXCR6 expression was investigated." (PMID 21203549, 2010). "Furthermore, we stimulated LOX melanoma cells stably expressing a CXCL16 variant that lacks the cytoplasmic tail due to truncation (LOX-ΔCXCL16) with recombinant and membrane expressed CXCR6, as well as control membrane fractions and did not observe any ERK1/2 phosphorylation either." (PMID 28698473, 2017). "This phenotypic co-association of CXCR6, a biomarker for asymmetric self-renewal in non-cancerous cells, with CSC activity in tumor-derived cells is evidence for a direct lineage relationship between TSSCs and CSCs in the case of melanocytic cells and melanoma, respectively." (PMID 21203549, 2010). "Regarding chemokine receptors, FGFR Mut melanoma expressed higher levels of CCR5, CCR7, CXCR3, CXCR4 and CXCR6 than their wild-type counterparts, but no statistical difference was observed (all P > 0.05)." (PMID 36426352, 2022). "However, in these CXCL16-transfected melanoma cells, we did not observe any regulation of proliferation upon stimulation with recombinant CXCR6, nor could we detect less cleavage of poly(ADP ribose) polymerase (PARP) after induction of apoptosis with 0.1 μg/mL camptothecin." (PMID 28698473, 2017). "LOX melanoma cells do not endogenously express CXCL16, nor CXCR6, and so, we generated LOX clones expressing transmembrane CXCL16 (LOX-CXCL16) or a C–terminally truncated version of transmembrane CXCL16 (LOX-ΔCXCL16) and a clone from the empty expression vector (LOX-pcDNA)." (PMID 28698473, 2017).
prostate carcinoma (28 papers, 2009 to 2025). A carcinoma that arises from epithelial cells of the prostate gland. "Activation of CXCR6 causes αvβ3 integrin clustering and hence an increase in tumor cell adhesion to bone marrow endothelial cells, as shown in prostate cancer cells." (PMID 33800554, 2021). "In addition, overexpression of CXCR6 is associated with poor prognosis in prostate cancer, gastric cancer, and renal cancer, especially prostate cancer CXCR6 which is an independent predictor of poor prognosis, and its overexpression is a risk factor." (PMID 33829065, 2021). "In addition to the association of CXCL16/CXCR6 with inflammatory infiltrates in prostate, our initial impression from analyzing more than 80 cases of prostate cancer was that expression of CXCL16 was highest in cancer cells surrounded by reactive stroma." (PMID 19690611, 2009). "Similar to CXCL16, an elevated CXCR6 expression is also associated with poorer overall survival for patients with cervical cancer, clear cell renal cell carcinoma, Ewing sarcoma family tumor, gastric cancer, gastrointestinal stromal tumors, hepatocellular carcinoma (p = 0.064), and prostate cancer." (PMID 33800554, 2021). "Another important element promoting prostate cancer bone metastases is CXCL-16, whose expression on prostate cancer cells led to the recruitment of mesenchymal stem cells (MSCs) from bone marrow, which express the CXCR6 chemokine receptor." (PMID 33535541, 2021). "Prostate cancer studies have shown lower CXCR6 expression in lymph node metastases than in the primary tumor." (PMID 33800554, 2021). "CXCL16 and its receptor, CXCR6, have been found to possess functional roles in various stages of prostate cancer metastasis including EMT, invasion, and tumor cell homing to secondary sites." (PMID 32585812, 2020). "In prostate cancer, MSCs can differentiate into CAFs after activation by C-X-C motif chemokine receptor 6 (CXCR6) and its ligand CXCL16." (PMID 33213510, 2020). "Overexpression of CXCR6 on implanted prostate cancer cell lines resulted in increased blood vessel formation in mice." (PMID 33552057, 2020). "Multiple studies have reported increased expression of both CXCL16 and CXCR6 in advanced stages of prostate cancer as well as in metastatic tissues, with expression pattern correlating with Gleason score of patients." (PMID 32585812, 2020). "While mainly expressed by antigen-presenting cells, CXCL16 is also produced by bone tissues including osteocytes and was shown to be involved in migration of CXCR6 expressing prostate cancer cells to this site." (PMID 31338489, 2019). "Another less prominently studied pathway is the CXCR6/CXCL16 molecular axis recently involved in homing of prostate cancer cells to the bones." (PMID 31338489, 2019). "CXCL16 induces the migration and invasion of the prostate cancer in vitro via CXCR6, which is increased in prostate and breast cancer cells and tumors, and is associated with aggressiveness and tumor stage." (PMID 29642534, 2018). "Previously, we demonstrated that CXCL16/CXCR6 chemokine axis induces prostate cancer progression by the AKT/mTOR signaling pathway." (PMID 25909173, 2015). "CXCR6 along with CXCL16 mediates pro-tumorigenic effect on prostate cancer cells by inducing the migration and proliferation of tumor associated leukocytes." (PMID 24259307, 2013). "Immunohistochemistry and/or immunofluorescence and confocal imaging of 121 human prostate specimens showed that CXCL16 and CXCR6 were co-expressed, both on prostate cancer cells and adjacent T cells." (PMID 19690611, 2009). "Overall, our findings suggesting pro-tumorigenic roles for CXCL16 and CXCR6 in prostate cancer are consistent with these published reports." (PMID 19690611, 2009). "Several of these reports focused on CXCR6 in prostate cancer, and like ours showed high expression of CXCR6 in prostate cancer cells." (PMID 19690611, 2009).
prostate carcinoma (continued). "Analysis of the 40-case array for levels of staining for CXCL16 and CXCR6 revealed that their expression by the cancer cells correlated with both high-stage and high-grade prostate cancer." (PMID 19690611, 2009). "Elevated CXCR6 expression has been observed in various cancer tissues, including prostate cancer, pancreatic ductal adenocarcinoma, and schwannoma, indicating that CXCR6 could be a promising therapeutic target." (PMID 40822973, 2025). "As alluded in a recent study, activation of the CXCL16/CXCR6 pathway promoted increased migration and invasion of prostate cancer cells via its ability to induce cytoskeletal protein reorganization through enhanced Ezrin phosphorylation and clustering of αvβ3 integrin structures." (PMID 32585812, 2020). "Overexpression of CXCR6 could facilitate cancer cell proliferation, invasion, and metastasis by regulating NF-κB pathway in prostate cancer." (PMID 33324682, 2020). "Our previous study also confirmed the excessive expression of CXCR6 protein in human native prostate cancer cells and the activation of CXCL16-CXCR6 pathway could promote the migration and invasion of PC3 and LNcap cells in vitro." (PMID 24897301, 2014). "A third paper demonstrated effects of CXCR6 on the growth of prostate cancer cell lines in mice." (PMID 19690611, 2009). "Our data correlating CXCL16 and CXCR6 with stage and grade of prostate cancer provide additional evidence that, in the prostate, inflammation is tumorigenic, and should stimulate the increasing interest in a possible tumor-promoting role specifically for CD4+ T cells." (PMID 19690611, 2009). "The co-expression of CXCL16 and CXCR6 on prostate cancer cells, and their correlation with cancer stage and grade, suggested that the ligand and receptor might enhance proliferation through an autocrine pathway." (PMID 19690611, 2009). "We found that CXCL16 and CXCR6 are expressed on T cells adjacent to prostate cancer cells." (PMID 19690611, 2009). "Our previous studies have demonstrated that CXCL16 signaling through CXCR6 may contribute to prostate cancer progression by serving as a proliferative signal and as a regulator of invasion; however, its role and mechanism of in BC development is still kept unsettled." (PMID 25909173, 2015). "In prostate cancer cells, a CXCR6/CXCL16 pair may activate the PI3K/Akt signal pathway." (PMID 23941552, 2013). "In addition, a correlation between the expression levels of CXCL16 and CXCR6 was found by analyzing an array of forty cases of prostate cancer, and CXCL16 and CXCR6 can be shown to be co-expressed on individual cancer cells by immunofluorescent confocal microscopy." (PMID 19690611, 2009). "In addition, CXCL16 enhanced proliferation of prostate cancer cell lines expressing CXCR6." (PMID 19690611, 2009). "Our preliminary screen for chemokine expression suggested a role for CXCL16, and we found that both CXCL16 and CXCR6 were co-expressed on cancer cells, that their levels of expression correlated with each other, and that these levels also correlated with high-stage and high-grade prostate cancer." (PMID 19690611, 2009). "This latter observation contrasts with our findings on the positive correlations between expression of CXCL16 and CXCR6 and high stage and grade for prostate cancer, and may reflect variable roles for inflammation in cancer depending on tumor type and stage of tumor development." (PMID 19690611, 2009). "In prostate cancer, high CXCL16 and CXCR6 expression is an independent predictor of poor clinical prognosis." (PMID 35468838, 2022). "The expression of CXCL16 and CXCR6 is also increased by the inflammatory response, in particular, by pro-inflammatory cytokines (TNF-α and IFN-γ) in prostate cancer cells." (PMID 33800554, 2021). "In NSCLC and prostate cancer, the increase of CXCL16 and CXCR6 is related with the poor prognostic features of patients." (PMID 33763372, 2021).
prostate carcinoma (continued). "In this study, we show involvement of CXC chemokine receptor 6 (CXCR6) and its only natural ligand CXCL16 in pathobiology of prostate cancer (PCa)." (PMID 26799186, 2016). "In prostate cancer cell lines, CXCL16 induced the expression of progangiogenic cytokines IL-8 and VEGF, while CXCR6 expression on implanted tumor cells lead to increased blood vessel formation in mice." (PMID 26021984, 2015). "Different from our previous study in human prostate cancer, there were a considerable proportion of cases (19/33) that also coexpressed CXCL16, the sole ligand for CXCR6." (PMID 24897301, 2014). "In the case of prostate cancer dissemination, or homing, to the bone, CXCR4 (CXC receptor 4), CXCR7 and CXCR6 are believed to have the greatest impact and are discussed in the remainder of this section." (PMID 21603150, 2011). "One paper, also like ours, demonstrated a positive correlation between CXCR6 levels and Gleason scores, reported CXCL16 expression in prostate cancers, and showed increased secretion of CXCL16 from prostate cell lines after treating with TNF-α." (PMID 19690611, 2009). "Screening for 37 chemokines in prostate cancer cell lines and xenografts revealed CXCL16, the ligand for the receptor CXCR6, as the most consistently expressed chemokine." (PMID 19690611, 2009). "In prostate cancer, inflammatory cytokines derived from the adjacent infiltrating CXCR6-positive T cells stimulate the production of CXCL16 by cancer cells and CXCL16 enhances the growth of CXCR6-expressing cancers and primary T cells." (PMID 36311728, 2022). "Furthermore, the expression of CXCR6 and its ligand CXCL16 in prostate cancer correlated with prognosis and CXCL16 enhanced the growth of CXCR6 expressing cancers." (PMID 24259307, 2013).
hepatocellular carcinoma (19 papers, 2015 to 2025). A malignant tumor that arises from hepatocytes. "A recent study of CXCR6 in resected hepatocellular carcinoma found high CXCR6 expression to be associated with reduced survival in a multivariate model, through stimulation of a pro-inflammatory tumor microenvironment." (PMID 26021984, 2015). "Clinical studies in hepatocellular carcinoma (HCC) have previously linked elevated CXCR6 expression with aggressive disease and poor survival." (PMID 41375019, 2025). "This increased to 10.2% when hepatoma cells were cocultured with CD8+CXCR6+ cells derived from untreated IHMCs." (PMID 36594467, 2023). "A study on the hepatocellular carcinoma SMMC-7721 cell line showed that the downregulation of CXCR6 expression reduces cell proliferation." (PMID 33800554, 2021). "Downregulation of CXCR6 in subcutaneously implanted hepatocellular carcinoma xenografts in mice, led to suppression of inflammatory infiltration and angiogenesis via inhibition of proinflammatory cytokine production." (PMID 33552057, 2020). "It has been demonstrated that the CXCL-16/CXCR6 axis promotes hepatocellular carcinoma invasiveness and induces a proinflammatory tumor environment for metastasis in various cancer types." (PMID 30483898, 2019). "In a hepatocellular carcinoma xenograft mouse model, suppression of CXCR6, a receptor for CXCL16, reduced tumor angiogenesis." (PMID 31527616, 2019). "CXCR6 expression was discerned in different hepatoma cell lines with various metastatic properties." (PMID 35978426, 2022). "Also, CXCR6 contributes to the microenvironment by inducing inflammatory cytokines, leading to the invasion and metastasis of hepatoma cells." (PMID 35978426, 2022). "CXCR6 may inhibit the occurrence of hepatocellular carcinoma by mediating the clearance of senescent hepatocytes by NKT cells and CD4+ T cells." (PMID 36090326, 2022). "Experiments on hepatocellular carcinoma SK-HEP-1 and HCCLM3 cells did show that the activation of CXCR6 causes a reduction in p38 MAPK activation and thus the activation of glycogen synthase kinase 3β (GSK3β), which leads to a reduction in the amount of β-catenin in the plasma membrane." (PMID 33800554, 2021). "Osteopontin (OPN) increases the expression of CXCR6 in hepatocellular carcinoma cells." (PMID 33800554, 2021). "However, studies on hepatocellular carcinoma have shown that CXCR6 is important in recruiting TAN to the tumor niche." (PMID 33800554, 2021). "As a step forward in the development of SBI-457-based CXCR6 antagonists, this study explores CXCR6 antagonism as a potential strategy to block crosstalk with sorafenib and β-catenin pathways and to increase response and overcome resistance to sorafenib in hepatocellular carcinoma." (PMID 41375019, 2025). "Similarly, knockdown of CXCR6 leads to reduced angiogenesis in murine hepatocellular carcinoma." (PMID 26021984, 2015). "Suppression of CXCR6, a receptor for CXCL16, has been found to reduce tumor angiogenesis in a hepatocellular carcinoma xenograft mouse model." (PMID 38172124, 2024). "We were able to induce FasL expression on 12.9% of CXCR6+CD8+ T cells, which led to killing 50% of hepatoma cells, indicating each cell has the potential to kill multiple (in our model, 3–4, over 24 hours) hepatocytes." (PMID 36594467, 2023). "CXCR6, C-X-C chemokine receptor type 6, is known to be preferentially expressed on CD8+PD-1high exhausted T cells in hepatocellular carcinoma (HCC) and is hypothesized to play a role in recruiting CD8+ T cells into the tumor microenvironment." (PMID 38023136, 2023). "In hepatocellular carcinoma, the gut microbiome uses bile acids as messengers to regulate chemokine CXCL16 levels on liver sinusoidal endothelial cells in order to control the accumulation of CXCR6+ hepatic natural killer T (NKT) cells that keep liver tumors at bay." (PMID 33262469, 2021).
hepatocellular carcinoma (continued). "However, the transitional L3 subgroup with strong anti‐tumor activity and the CXCR6+CD16+L4 subgroup are absent in Hepatocellular carcinoma (HCC) and peri‐tumoral liver tissue." (PMID 40062730, 2025). "Also, in hepatocellular carcinoma SK-HEP-1 and the HCCLM3 cells, changes in CXCR6 expression do not affect tumor cell proliferation." (PMID 33800554, 2021).